MTX3 (metaxin 3)
Description:
Could function in transport of proteins into the mitochondrion.
Tractability: PROTAC: ubiquitination databases record sites on it; its protein half-life has been measured.
Gene: Protein-coding gene on chromosome 5 (79,976,716 to 79,991,262, reverse strand). Ensembl gene ENSG00000177034.
Subcellular location: Mitochondrion; Mitochondrion outer membrane
Subcellular location (Human Protein Atlas): Mitochondria
Gene Ontology:
Biological process: inner mitochondrial membrane organization; mitochondrial outer membrane translocase complex assembly; protein insertion into mitochondrial outer membrane; mitochondrion organization
Cellular component: MIB complex; mitochondrion; SAM complex; mitochondrial outer membrane
Genetic constraint (gnomAD): Loss-of-function variants: 11 observed, 19.14 expected, observed/expected ratio (o/e) 0.57, 90% interval 0.36 to 0.95. The upper end of that interval is the gene's LOEUF score, 0.95, which puts it in group 4 of 6, group 1 being the genes least tolerant of losing a copy. Missense variants: 243 observed, 224.01 expected, observed/expected ratio (o/e) 1.08, 90% interval 0.98 to 1.21. Synonymous variants: 93 observed, 85.74 expected, observed/expected ratio (o/e) 1.08, 90% interval 0.92 to 1.29.
Homologues: Orthologues: chimpanzee MTX3 (100% identical), macaque MTX3 (99% identical), dog MTX3 (96% identical), guinea pig MTX3 (92% identical), mouse Mtx3 (90% identical), rat Mtx3 (90% identical), pig MTX3 (88% identical), rabbit MTX3 (73% identical), tropical clawed frog mtx3 (70% identical), zebrafish mtx3 (59% identical), Caenorhabditis elegans mtx-1 (29% identical), Drosophila melanogaster CG9393 (27% identical). Paralogues in human: MTX1 (47% identical), MTX2 (24% identical), FAXC (20% identical).